CD44 (CD44 molecule (IN blood group))
Diseases named in the same sentence as CD44 in open-access papers (continued):
Sharing a sentence is not in itself a finding about the gene and the disease.
breast carcinoma (continued). "Interestingly, TG2 has been shown to increase CD44 activity in breast cancer cells, regulating the promotion of stem cell phenotype and metastatic potential, and inhibition of TG2 lead to depleted CSC surface antigens such as CD44 in renal cell carcinoma." (PMID 34205140, 2021). "Similarly, ectopic expression of miR-221/222 promotes breast cancer cell proliferation, migration, invasion, enriched proportion of CD44(+)/CD24(-) BCSCs and improves mammosphere formation capacity via downregulating PTEN." (PMID 33413418, 2021). "We isolated the compound 6-methoxymellein, which inhibits the proliferation and migration of breast cancer cells, reduces mammosphere growth, decreases the proportion of CD44+/CD24− cells in breast cancer cells and decreases the expression of stemness-associated proteins c-Myc, Sox-2 and Oct4." (PMID 32977636, 2020). "Notably, the expression of CD44 was positively correlated with estrogen receptor (ER) activity in PIK3CA-mutant breast cancers, and ER-dependent transcription upon PI3Kα pathway inhibition was in turn mediated by CD44." (PMID 33024087, 2020). "Because the MDA-MB-231 cells may be too aggressive to model early tumor formation in breast cancer, we investigated whether CD44 expression impacted metastatic lesion formation in vivo using a tail vein injection model." (PMID 32455980, 2020). "The CD44+/CD24- population of breast cancer cells was assayed under machilin D treatment." (PMID 32033472, 2020). "The physicochemical properties, antitumor efficacy, and mechanisms of action of the HA-DOX-CDDP micelles were investigated using CD44- normal fibroblast cells (NIH-3T3) and CD44+ breast cancer cells (4T1) in vitro, and in mice bearing 4T1 breast tumors in vivo." (PMID 32982750, 2020). "Thus, CD44 KO in breast cancer cells altered the expression of genes not only involved in cell adhesion but also cytokine activity." (PMID 32455980, 2020). "Furthermore, Cav-1 knockdown significantly increased the CD44+/CD24−/low subpopulation in the breast cancer xenograft formed by the reinoculated BCSCs, whereas Cav-1 overexpression decreased this subpopulation." (PMID 32528105, 2020). "The CD44+CD24− subpopulation was the first identified as CSC in breast cancer." (PMID 32435546, 2020). "Thus, the first report demonstrating that CTL can recognize and eliminate CSC populations was using CSC-enriched MCF-7 breast cancer and SK-OV-3 ovarian cancer cells (CD44+/CD24lo/CD133+) after treatment with 5-fluorouracil and paclitaxel." (PMID 32850424, 2020). "Two CSF ctDNA samples had a gain of ERBB2 (HER2) copy number from a parotid carcinoma patient, while an increase in CD44 copy number was identified in three patients, in which each patient has breast cancer, gastric cancer and unknown cancer, respectively." (PMID 32711494, 2020). "A subpopulation of breast cancer cells exhibit the surface phenotype CD44+CD24−." (PMID 32630026, 2020). "CD44 mRNA and protein overexpression were observed in the basal subtype of breast cancer." (PMID 32961774, 2020). "CD44 KO had little effect on cell survival in both breast cancer cell lines." (PMID 32455980, 2020). "Flow cytometry data showed that all parental cancer cell lines and hybrid clone cells exhibited the putative breast cancer stem/ initiating cell phenotype CD44+/CD24−/low, which has been demonstrated to determine a highly tumorigenic breast cancer cell population." (PMID 32430004, 2020). "The cell surface marker of breast CSCs is CD44+/CD24− of breast cancers." (PMID 32977636, 2020). "Moreover, cell sorting of MCF-7 breast cancer cells using the stem marker CD44 revealed that CD44+ cells had higher levels of STAT1 expression than CD44− cells." (PMID 32296435, 2020). "Also in breast cancers, the percentage of CD44+/CD24−/CK+/CD45− cells was shown to be increased in malignant lesions compared to non-malignant lesions." (PMID 32849491, 2020). "Breast cancer cells are well known to overexpress CD44 proteins." (PMID 33014359, 2020).
breast carcinoma (continued). "However, it has also been implicated in tumor progression through stimulating epithelial to mesenchymal transition (EMT) and breast cancer stemness through Rb and CD44." (PMID 32933207, 2020). "In general, SCLC CTC spheroids are not sensitized to salinomycin and the difference in chemosensitivity between single cells and aggregates is far lower than the 100fold disparity observed in breast cancer mammospheres and tumor cells exhibiting a CD44+/CD24− CSC phenotype." (PMID 31446534, 2020). "Furthermore, the IL-6/JAK/STAT3 pathway has been shown to be important for the proliferation of CD44+CD24− stem cell–like breast cancer cells." (PMID 32328465, 2020). "Furthermore, a previous study showed that CD44 expression was significantly inhibited by miR-512-3p in breast cancer." (PMID 33028341, 2020). "Combined, these data indicate that the majority of CTCs found in metastatic breast cancer patients maintain a stem-like (CD44+/CD24−) state, while staying mitotically inactive; whereas a smaller sub-population of CTCs are of an epithelial (PanCK+) phenotype, with a higher proliferative index." (PMID 32575420, 2020). "The NPs-αIL6R Ab-CD44 specifically modified the immune environment in primary tumor by inhibiting the infiltration of TAMs to form a tumor microenvironment unfavorable for metastasis and achieved a significant effect to inhibit the metastasis of breast cancer." (PMID 34138136, 2020). "Interestingly, in breast cancer, it has been shown that CD44 was associated with longer disease-free-survival (DFS) in estrogen-receptor (ER) positive women, while CD44 positive tumors were associated with poor outcome in ER-negative patients." (PMID 32154167, 2020). "Therefore, we performed flow cytometry analysis to examine the CD44/CD24 population in four different kinds of breast cancer cells (BT-549, MDA-MB-231, Hs-578T, and MCF-7 cells) 3 to 5 days after CRISPRMAX-PKAs delivery." (PMID 33374889, 2020). "Breast cancer stem cells identified by CD44+CD24− cells formed tumors into Nod/Scid mice." (PMID 33233552, 2020). "The present study evaluates the expression of CD44 in primary HER2-positive breast cancer." (PMID 32986353, 2020). "A meta-analysis of enrolling a total of 1747 breast cancer cases displayed that there was no any association between CD44 expression and OS." (PMID 33303029, 2020). "Moreover, they confirmed that downregulation of miR-27b is associated with the generation of the high tumor seeding ability and chemoresistance population of luminal-type breast cancer cells, CD44+/CD24−." (PMID 32512882, 2020). "Furthermore, the report found that loss of EphA5 resulted in higher expression of cancer stem cell (CSC) markers in HER2-positive breast cancer cells, including CD44+/CD24-/low, NANOG, CD133+." (PMID 31956298, 2020). "Also, we modified the MCF-7–derived exosomes loaded with siRNA against CD44 to observe the effects of targeting reduced CD44 expression in luminal A breast cancer cells." (PMID 32760666, 2020). "In basal/HER2+ breast cancer cell lines, Menendez and colleagues showed that EMT-associated transcription factors (Snail2 and Slug) enhance resistance to trastuzumab via inducing a BCSC phenotype (CD44+CD24−/low)." (PMID 32391382, 2020). "In this study, an HA-based nano-carrier incorporating doxorubicin (DOX) and cisplatin (CDDP) was synthesized as a CD44-targeting anti-cancer drug delivery system, and its tumor inhibition effects against CD44+ breast cancer cells were evaluated in vitro and in vivo." (PMID 32982750, 2020). "To further investigate the possibility that TMPs expressing CD44 could be found in breast cancer patients following chemotherapy, we collected plasma samples from 15 breast cancer patients at baseline or 24 h after PTX chemotherapy administration." (PMID 33050539, 2020). "In the case of breast cancer, CD44 and BRCA2 showed a strong positive correlation (p = 0.003)." (PMID 32610620, 2020).
breast carcinoma (continued). "The effect of caudatin treatment on the population of CD44+/CD24− breast cancer cells was assayed." (PMID 32570844, 2020). "In agreement with the in vitro results, organotropic breast cancer cell lines show intense and strong staining for both CD44 (Figure 5C6–C8 in comparison to C5 and Figure 5M6–M8 in comparison to M5) and CD49f (Figure 5C10–C12 in comparison to C9 and Figure 5M10–M12 in comparison to M9)." (PMID 33396951, 2020). "Additionally, the mesenchymal marker CD44 was identified to significantly positively regulate PD-L1 expression in breast cancer and non-small cell lung cancer." (PMID 33028341, 2020). "Notably, production of the chemokine CCL2 within breast cancer cells was significantly decreased in conditions where either CD44 was deleted or HA was depleted." (PMID 32455980, 2020). "Besides, CD44 positively modulates the expression of nuclear factor erythroid 2-like 2 (a key regulator of antioxidant genes) in doxorubicin-resistant breast cancer cell lines." (PMID 33303029, 2020). "Additionally, betavulgarin reduced the size of the CD44+/CD24− subpopulation in breast cancer cells." (PMID 32630026, 2020). "CD44 is a key stem cell marker in mammary malignancies and it has been shown that as few as 100 CD44(high) cells may promote tumorigenesis in breast cancer." (PMID 32245259, 2020). "The expression of the candidate target exosomic CD44 in DOX-resistant cells (A/Exo) was higher than in parental breast cancer cells (S/Exo), and the increasing levels of exosomic CD44 (21.65-fold) were higher than those of cellular CD44 (6.55-fold) (all p < 0.05)." (PMID 32760666, 2020). "First, we analyzed by flow cytometry whether the percentage of MDA-MB-231 and MCF-7 breast cancer cells displaying the CD44+/CD24– phenotype was changed by HS2ST1 and HS3ST2 overexpression." (PMID 33102470, 2020). "However, some other studies have shown contrary or contradictory results for the role of CD44 in tumor-related clinical outcomes, such as breast cancer and glioblastoma." (PMID 33303029, 2020). "Similarly, Hong and colleagues found that FH535, another β-catenin/TCF inhibitor, significantly suppressed tumor sphere formation and the CD44+/CD24− BCSC subpopulation in mouse breast cancer cells." (PMID 32391382, 2020). "This suggests the prognosis value of CD44 protein in serum as a potential marker of breast cancer." (PMID 33224883, 2020). "Of note, the breast CSCs enriched from the breast cancer cell lines have been previously shown to contain functional cancer stem cells with high CD44 and low CD24 expression and retain high tumorigenic activity when injected into the mammary fat pad of SCID mice." (PMID 32260399, 2020). "In conclusion, breast cancer cells could spread resistance capacity by the intercellular transfer of proteins, especially CD44, via exosomes." (PMID 32760666, 2020). "Indeed, a high CD44/CD24 ratio in breast cancer has been shown as an important breast cancer prognosis predictor and also to be enriched in circulating tumor cells and in distant metastases, such as in liver, bone, and lung." (PMID 33182375, 2020). "Our study suggested that CD44 cross-linking could elevate p-Moesin expression and further affect migration and invasion of breast cancer cells." (PMID 33292278, 2020). "Given the accumulating evidence that the microenvironment supports tumor growth, we investigated hyaluronan (HA)-CD44 interactions within breast cancer cells, to determine whether this axis directly impacts the formation of an inflammatory microenvironment." (PMID 32455980, 2020). "In addition, we detected the uptake of 5K-HA-HPPS by B16F10 melanoma cells, CT26 colon tumour cells and E0771 breast cancer cells, which also express CD44 and SR-B1." (PMID 33014359, 2020). "Moreover, there was a positive correlation between the MTDH and CD44 expression levels in The Cancer Genome Atlas breast cancer database." (PMID 31979093, 2020).
breast carcinoma (continued). "It was previously shown that the cell fraction with the CD44+/CD24-/Lin- phenotype in breast cancer patient tissues could recapitulate tumor burden in mice." (PMID 33488948, 2020). "In the tumor cells from breast cancer survivors undergoing chemotherapy, the proportion of BCSCs with CD44+CD24− phenotype after chemotherapy was significantly increased compared with that before chemotherapy, and the ability of BCCs to form microspheres was also improved." (PMID 31300015, 2019). "As extracellular matrix, glycosaminoglycan hyaluronan (HA) could bind its surface receptor adhesion molecule CD44 which is strongly expressed on breast cancer." (PMID 30691317, 2019). "Moreover, these putative CSCs, such as those in pancreatic cancer (ALDH+ cells), colon cancer (CD133+ cells), breast cancer (CD44 + CD24− cells), and GC (CD44+ cells) are sensitive to Hh inhibitors." (PMID 31775795, 2019). "Reduced expression of CD44 and NF-κβ genes in treated cells were in accordance with previous studies and indicated the possibility that these two molecules interact in a special way during breast cancer progression." (PMID 31847364, 2019). "Supporting this notion, the nanoparticles of anti- CD44 Ab encapsulating anti-IL-6R Ab target the TME and CD44+ BCSCs that inhibit the metastatic niche of triple-negative and luminal breast cancer in two mouse models, namely syngeneic BALB/c mice bearing 4 T1 cells and transgenic MMTV-PyMT mice." (PMID 30885232, 2019). "Similarly, in breast carcinoma tissues, a direct correlation between the overexpression of both CD44 and PrPC was detected in patients unresponsive to neoadjuvant chemotherapy." (PMID 31752162, 2019). "Moreover, both CD44 and PrPC are overexpressed in breast cancer cell lines resistant to doxorubicin, and PrPC silencing, disrupting this interaction, allows the recovery of drug sensitivity." (PMID 31752162, 2019). "Similarily to the findings in breast cancer, we here demonstrate an association of AF1q with both WNT and STAT signaling in the sense that the patients with AF1q-positive EC show enhanced tumoral levels of both proposed downstream targets CD44 and pYSTAT3." (PMID 31671695, 2019). "Furthermore, preferential killing of CD44+/CD24−/low breast cancer cells or BCSCs induced by MET can be sufficient to overcome the primary resistance to Herceptin® in HER2+ breast cancer xenografts." (PMID 31877620, 2019). "For instance, CSCs expressing CD44 and ALDH1 are strongly correlated with a high tumorigenic and chemoresistant phenotype, whereas CSCs expressing CD133 are associated with a high metastatic phenotype in breast cancer." (PMID 31726667, 2019). "Moreover, the downregulation of CD44 in breast cancer cells showed a higher sensitivity to doxorubicin." (PMID 31357721, 2019). "Our previous studies show that ESA+CD44+CD24-/low breast cancer cells have stem-like cell characteristics and found that BCSCs on the conventional chemotherapy drug docetaxel, endocrine therapy drugs such as letrozole and targeted therapy trastuzumab, have a certain resistance." (PMID 30906504, 2019). "ALDH+ and CD44+/CD24− are two major CSC subpopulations identified in human breast cancer cells." (PMID 31695034, 2019). "CSCs in breast cancer were first identified as cells with a CD44+CD24−/low phenotype." (PMID 31137841, 2019). "Breast cancer cells with CD44+/CD24−/low specifically have CSC properties." (PMID 31877620, 2019). "In addition to breast cancer, CD44+ESAlow cells with increased metastatic potential (upon EMT), linked to low ROS levels, as compared to their non-EMT counterparts, have been described for oral and skin carcinomas, as well as prostate cancer." (PMID 30967773, 2019). "Induction of cell migration in triple-negative MDA-MB-231 breast cancer cells led to reduced affiliation of CD44 with lipid raft, and this was accompanied by increased association of CD44 with active ezrin, a membrane-cytoskeleton linker, in the nonraft fraction." (PMID 31416894, 2019).
breast carcinoma (continued). "At the cellular level, HPPDC nanoparticles successfully overcame drug resistant in breast cancer through multiple mechanisms including CD44-mediated cellular internalization, efficient intracellular drug release, and notably suppressed P-gp and COX-2 expressions." (PMID 31623608, 2019). "We hypothesize that MET preferentially kills breast cancer initiating CD44+/CD24–/low cell subpopulation, leading to increased cell death." (PMID 31877620, 2019). "This study also provides new insights into anti-CD44 therapy in tamoxifen-resistant breast cancer." (PMID 31416894, 2019). "In studies with breast cancer cell lines in vitro and in vivo, disulfiram not only diminished mammosphere formation and reduced CD44+CD24- and CD49f+CD24+ subpopulations, but also managed to reverse paclitaxel and cisplatin resistance of triple-negative breast cancer (TNBC)." (PMID 30967773, 2019). "Interestingly, the adhesion molecule CD44 that regulates the aggressive phenotype of breast cancer cells seem to be a common target of AS." (PMID 31666932, 2019). "Mammosphere assay, FACS analysis for CD24-/CD44+ population and/or serial dilution xenograft mouse model might be performed to confirm the effect of metformin on stemness in breast cancer cells." (PMID 30625181, 2019). "In 2003, Al-Hajj first identified that the cell fraction with the CD44+/CD24−/Lin- phenotype in breast cancer patient tissues could recapitulate tumor burden in mice." (PMID 31324052, 2019). "The proportions of CD44+/high/CD24−/low cell populations across the PMC42 cell lines were compared with five other breast cancer cell lines (MCF-7, T47D, MDA-MB-468, MDA-MB-231 and SUM-159) and the expression of these surface markers was simultaneously assessed by FACS analysis." (PMID 31430931, 2019). "In breast cancer cells, sequential cleavage of CD44 resulted in nuclear accumulation of CD44-ICD." (PMID 31331331, 2019). "In addition, BMP-4 upregulated the sphere forming efficiency, colony formation efficiency, and the expression of cancer stem cell markers, such as Nanog and CD44, in the breast carcinoma cell line MDA-MB-231." (PMID 31409851, 2019). "CD44+/CD24− breast cancer cells are widely accepted to act as the stem cell-like population." (PMID 31139014, 2019). "HNRNPM was found to be upregulated in breast cancer, and it could promote breast cancer invasion and metastasis via regulating CD44 alternative splicing." (PMID 31355266, 2019). "Furthermore, SR splice factor TRA2β is overexpressed in invasive breast cancer and induces exon v4 and v5 inclusion, suggesting that besides the standard CD44 isoform also the v4 and v5 isoforms are related to increased invasion and metastasis formation." (PMID 31666932, 2019). "CD44+/CD24− breast cancer cells have stem/progenitor cell properties." (PMID 31195298, 2019). "Breast cancer stem cells (BCSCs) were a tumorigenic subset of breast cancer cells first isolated from human breast tumors with the expression of the surface markers CD44+/CD24−, which are the radical cause of drug resistance, tumor relapse, and metastasis in breast cancer." (PMID 30792382, 2019). "Co-expression of CD44 and CD24 is frequently observed in basal/epithelial breast cancer cells and CD44+/CD24+ cells have shown to be more invasive and tumorigenic than CD44+/CD24neg cells and possess stemness characteristics of self-renewal and differentiation in multiple cancer types." (PMID 31217901, 2019). "ALDH1+ CD44+ Ki67+ CSCs, detected in a central position in mammary tumors, might be hypothetical CSC1s, constituting about 0.084% of the tumor mass." (PMID 30899759, 2019). "Based on our knowledge, there are no studies reporting the association between CD44 polymorphisms and breast cancer risk as well as clinico-pathological properties in Iranian patients." (PMID 29483847, 2018). "Furthermore, we confirmed a positive correlation between the expression level of ERα and CD44 in our established paclitaxel‐resistant ER+ breast cancer cells." (PMID 30179299, 2018).